LINC01569 (long independently transcribed non-coding RNA 1569)
Synonyms: TCONS_00024567
Gene: Long non-coding RNA gene on chromosome 16 (4,243,943 to 4,253,855, reverse strand). Ensembl gene ENSG00000262468.
Diseases named in the same sentence as LINC01569 in open-access papers:
LINC01569 is named in the same sentence as 2 diseases in open-access papers, as found by Europe PMC text mining. Sharing a sentence is not in itself a finding about the gene and the disease. The quoted sentences say what the papers report.
hypopharyngeal carcinoma (1 paper, 2023). Carcinoma, predominantly squamous cell, arising from the epithelial cells of the hypopharynx. "Therefore, we conclude that LINC01569 is responsible for regulating the M2 polarization of macrophages and subsequently causes abnormal immune regulation in hypopharyngeal carcinoma." (PMID 37325064, 2023). "Our findings revealed that LINC01569 regulates macrophage polarization, resulting in the occurrence and development of hypopharyngeal carcinoma through the miR-193a-5p/FADS1 signaling axis." (PMID 37325064, 2023). "Interestingly, LINC01569 enhancement was observed in the TAMs of hypopharyngeal carcinoma tissues, in contrast to the corresponding tumor-adjacent tissue." (PMID 37325064, 2023). "Therefore, the differential expression of LINC01569 in hypopharyngeal carcinoma may depend on the abnormal expression of LINC01569 in TAMs." (PMID 37325064, 2023). "LINC01569 downregulation restrains macrophages from polarizing toward M2 through the miR-193a-5p/FADS1 signaling axis, thereby helping tumor cells escape inherent immune surveillance and promoting the occurrence and development of hypopharyngeal carcinoma." (PMID 37325064, 2023).
LINC01569 also shares sentences with these, for which no sentence is quoted: tumor (1 paper).